ISG20 (interferon stimulated exonuclease gene 20)
Description:
Interferon-induced antiviral exoribonuclease that acts mainly on single-stranded RNA. Exhibits antiviral activity against RNA viruses including hepatitis C virus (HCV), hepatitis A virus (HAV) and yellow fever virus (YFV). Inhibition of several viruses such as chikungunya virus (CHIKV) does not involve the degradation of viral RNAs, but rather the inhibition of translation of viral proteins (By similarity). Exerts a translational control over a large panel of non-self RNA substrates while sparing endogenous transcripts. This activity correlates with the protein's ability to localize in cytoplasmic processing bodies. May also act as master regulator of over hundred interferon stimulated genes leading to viral genome translation inhibition (By similarity). May play additional roles in the maturation of snRNAs and rRNAs, and in ribosome biogenesis.
Synonyms: HEM45; CD25
Tractability: Small molecule: a structure with a bound ligand is known. PROTAC: ubiquitination databases record sites on it; its protein half-life has been measured.
Gene: Protein-coding gene on chromosome 15 (88,635,618 to 88,656,483, forward strand). Ensembl gene ENSG00000172183.
Subcellular location: Nucleus; Nucleus, nucleolus; Cytoplasm; Nucleus, Cajal body; Cytoplasm, P-body
Pathways (Reactome):
Immune System: Interferon alpha/beta signaling
Gene Ontology:
Molecular function: 3'-5'-RNA exonuclease activity; exonuclease activity; single-stranded DNA 3'-5' DNA exonuclease activity; U1 snRNA binding; U2 snRNA binding; U3 snoRNA binding; exoribonuclease II activity; nucleic acid binding
Biological process: defense response to virus; DNA catabolic process; negative regulation of viral genome replication; response to virus; RNA catabolic process; RNA processing
Cellular component: Cajal body; cytoplasm; nucleolus; nucleus; PML body; nucleoplasm; P-body
Genetic constraint (gnomAD): Loss-of-function variants: 8 observed, 12.05 expected, observed/expected ratio (o/e) 0.66, 90% interval 0.39 to 1.2. The upper end of that interval is the gene's LOEUF score, 1.2, which puts it in group 5 of 6, group 1 being the genes least tolerant of losing a copy. Missense variants: 243 observed, 260.57 expected, observed/expected ratio (o/e) 0.93, 90% interval 0.84 to 1.04. Synonymous variants: 110 observed, 106.09 expected, observed/expected ratio (o/e) 1.04, 90% interval 0.89 to 1.22.
Homologues: Orthologues: chimpanzee ISG20 (100% identical), rabbit ISG20 (83% identical), rat Isg20 (80% identical), macaque ISG20 (80% identical), dog ISG20 (76% identical), guinea pig ISG20 (76% identical), pig ISG20 (75% identical), mouse Isg20 (73% identical), tropical clawed frog aen (46% identical), zebrafish isg20l2 (44% identical). Paralogues in human: AEN (52% identical), ISG20L2 (48% identical), REXO4 (35% identical), REXO1 (29% identical), REXO5 (28% identical).
Diseases named in the same sentence as ISG20 in open-access papers:
ISG20 is named in the same sentence as 86 diseases in open-access papers, as found by Europe PMC text mining. Sharing a sentence is not in itself a finding about the gene and the disease. The quoted sentences say what the papers report.
viral infection (32 papers, 2011 to 2026). "First, we found a significant inhibitory effect of PRV on the expression of RACK1, IFN‐β, ISG15, and ISG20 in cells during the late phase of viral infection, indicating a potential association between RACK1, IFN‐I pathway, and PRV infection." (PMID 41395239, 2025). "Lastly, this mechanism of action is conserved in the ISG20 murine ortholog, whose genetic ablation results in mice with increased susceptibility to viral infection." (PMID 31600344, 2019). "Having observed that ISG20 overexpression stimulates the expression of genes associated with viral infection and tumorigenesis, we next analyzed the effect on the stability of cellular transcripts, as the exonuclease domain has been shown to be important for ISG20 function." (PMID 41511982, 2026). "Finally, these functions are conserved in the ISG20 murine ortholog, whose genetic ablation results in mice with increased susceptibility to viral infection." (PMID 31600344, 2019). "The effect of overexpressed ISG20 was shown to be dependent on its exonuclease activity and attributed to an interaction with NP, as shown by immunoprecipitation using overexpressed ISG20 and viral infection." (PMID 33810083, 2021). "Overall, our study reveals a novel role of ISG20 as a translational modulator of foreign genetic material playing important functions during viral infection in vivo." (PMID 31600344, 2019). "Such information will aid the function study of ISG20 against viral pathogens in host innate defense, and ISG20 has potentials to be developed into a therapeutic agent for viral diseases including hepatitis B." (PMID 28399146, 2017). "It is hypothesised that ISG20 may modulate the cochlear response to viral infections or inflammatory stimuli, thereby indirectly influencing hair cell or auditory neuron survival related to ARHL." (PMID 41255877, 2025). "Among ISGs that act as antiviral effectors and that are thus thought to inhibit virus infection by directly binding or altering one of their components is the interferon‐stimulated gene 20 kDa protein (ISG20), also known as human estrogen‐regulated transcript 45 protein (HEM45)." (PMID 35174977, 2022). "We also show that IL22 reduces the expression of viral entry receptors (e.g. ACE2, TMPRSS2, DPP4, CD46 and TNFRSF14), increases the expression of anti-viral proteins (e.g. RSAD2, AOS, ISG20 and Mx1) and, consequently, reduces the viral infection of neighboring cells." (PMID 34045640, 2021). "ISG20 is activated by IFN-β early in viral infection, while YTHDC2 recruits ISG20 to degrade IFN-β mRNA later in the disease progression." (PMID 40066451, 2025). "Meanwhile, the transcriptional levels of interferon-stimulated genes (ISGs) such as ISG15, ISG20, OAS1, OAS2, MX1, and MX2 were significantly up-regulated, and these ISGs play a crucial role in resisting viral infection." (PMID 41153955, 2025). "The expression of ISG20 and ISG56 is induced after viral infection, and both these genes have the function of inhibition of viral replication (17, –, 19)." (PMID 35604142, 2022). "Subsequently, we visualized how those terms were linked to one another, which showed that for the horse there was a strong connection between liver pathology and viral infection, most likely driven by the activation of ISGs such as OAS1, MX1, and ISG20." (PMID 35527255, 2022). "In addition, the ISG20 protein showed a highly conserved sequence across different species, including humans, chimpanzee, Rhesus monkey, cows, dog, mice, and rats, suggesting that ISG20 may possess a similar potential function in inhibiting viral infection in other species." (PMID 36177004, 2022). "Especially, many ISGs were modified with ubiquitin during viral infections such as MX1, MX2, OAS2, ISG15, and ISG20, which has rarely been reported before." (PMID 36071039, 2022). "lncRNA NEAT, 7SL, NRAV, lnc-ISG20, and CCR5AS have been reported to regulate the innate immune responses to virus infection." (PMID 32153544, 2020).
viral infection (continued). "ISG20 and ISG15 possess direct antiviral activity, and have been shown to mediate protection in several different viral infection models." (PMID 30158514, 2018). "Among these, the expression of Mx1, Mx2, TRIM22, WARS, ISG15, ISG20, UBA7, DDX58, and OAS1-3 were up-regulated, representing an increased innate immune response against viral infections." (PMID 25883591, 2015). "For example, lnc-ISG20 inhibits the replication of influenza virus by enhancing the expression of ISG-20, although this lncRNA can also be exploited by the virus to promote viral infection." (PMID 40237496, 2025). "Depletion of endogenous ISG20 led to increased viral infection in the absence of IFN treatment, suggesting that the basal level of ISG20 was sufficient to restrict BUNV." (PMID 38711929, 2024). "For example, lnc-ISG20 and ISR function as interferon-stimulated genes (ISGs), and LncRNA-155, NEAT1, SAAL, RDUR, AVAN and IVRPIE can suppress IAV replication by promoting innate immune responses to viral infection." (PMID 37308824, 2023). "Products of ISG15 and ISG20 are functionally different proteins—a ubiquitin-like modifier and an exonuclease, respectively, although both ISG15 and ISG20 belong to interferon-stimulated genes and are involved in the innate immune response to viral infection." (PMID 37998351, 2023). "Furthermore, 14 proteins that were upregulated after virus infection—including TNFaIP3, HNRNPH2, RSAD2, ISG20, IDO1, and KCNN4—also exhibited significantly increased mRNA levels relative to uninfected cells (p < 0.05)." (PMID 36423196, 2022). "Network analysis of ISG20 overexpression highlighted a pattern similar to that seen with viral infection or IFN responses but without the induction of primary signaling components of type I, II, or III IFN or their receptors." (PMID 30232164, 2018). "Cellular localization of ectopically expressed ISG20 was consistent with the published literature, forming dense nuclear puncta in confocal micrographs, and this localization did not change with virus infection (data not shown)." (PMID 30232164, 2018). "In the absence of viral infection or IFN gene induction, ectopic expression of ISG20, but not a nuclease domain mutant, induced expression of a suite of genes, many of which have described or predicted antiviral activity." (PMID 30232164, 2018).
COVID-19 (19 papers, 2020 to 2025). A disease caused by infection with severe acute respiratory syndrome coronavirus 2. "Genes that were found to be upregulated in the early COVID-19 mortality cases and involved with the interferon (ISG20, IRF1, GBP2) and NF-κB (NFKB2, NFKBIA, TNFAIP3) pathways showed linear decline with longer symptomatic interval." (PMID 35446789, 2022). "The present study analyzed ISG20 expression, isoform information, survival rate, methylation patterns, immune cell infiltration, and COVID-19 outcomes in healthy and cancerous individuals." (PMID 36177004, 2022). "In addition, neutrophil-cluster 6 showed particularly low and high expression of Il1r2 and Isg20, respectively, thereby recapitulating the phenotypes seen for immunosuppressive and IFNactive neutrophils in the peripheral blood of COVID-19 patients." (PMID 35339689, 2022). "Therefore, the expression and distribution of ISG20 may explain the differences in COVID-19 severity after the SARS-CoV-2 invasion." (PMID 36177004, 2022). "In module 2, enhanced expression of glycolysis (GAPDH and TPI1) and IFN response (IFITM2, IFITM1, IFITM3, IFNGR2, and ISG20) genes in human COVID-19 patients, particularly severely ill patients, may promote the differentiation of unswitched memory B cells into plasmablasts." (PMID 33936072, 2021). "Protein-protein interaction analysis of the effects exerted by anti-COVID-19 vaccination revealed one cluster comprised mainly of various HLA types, i.e., HLA-DOB, HLA-F, HLA-G, and ISG20." (PMID 39744634, 2024). "Thus, targeting ISG20 may be a potential therapeutic strategy for treating COVID-19." (PMID 38057373, 2023). "The interferon (IFN)-stimulated 15 KDa protein (ISG15) had the largest increase in serum of COVID-19 patients, followed by several other IFN-induced proteins, such as ILF2, MX1, ISG20, LAP3, and UBE2L6." (PMID 37739942, 2023). "When we analyzed DEGs, severe COVID-19 was characterized by up-regulation of various ISGs, including ISG15, IFITM1/2/3, and ISG20." (PMID 32651212, 2020). "Classical monocytes in severe COVID-19 were found to be accompanied by the IFN-I response that was characterized by the up-regulation of various interferon-stimulating genes (ISGs), including ISG15, IFITM1/2/3, ISG20, IFI27, and MX1 when compared to mild COVID-19." (PMID 36159873, 2022). "Specifically, the NK2.1 cells of elderly patients have high expression of genes with functional annotations related to response to type I interferon (e.g. ISG15, ISG20, etc.)compared to that of NK2.1 cells from young COVID-19 patients (P = 1.11e−36, Wilcoxon rank-sum test)." (PMID 35501841, 2022). "OASL, RSAD2, ISG20, IFI16, and IFIT1 were not previously annotated in the COVID-19 KEGG pathway." (PMID 38580667, 2024).
glioma (14 papers, 2015 to 2025). A benign or malignant brain and spinal cord tumor that arises from glial cells (astrocytes, oligodendrocytes, ependymal cells). "Regarding IDH mutation status, ISG20 expression was markedly enhanced in glioma tissues with wild-type IDH (P < 0.001)." (PMID 37380984, 2023). "Elevated ISG20 expression is associated with the malignant phenotype of glioma and marginal therapeutic efficacy." (PMID 37380984, 2023). "Using bioinformatics, we comprehensively illustrated the potential function of ISG20, its predictive value in stratifying clinical prognosis, and its association with immunological characteristics in gliomas." (PMID 37380984, 2023). "Above results would inspire the further exploration of issues regarding the association of ISG20 and other glioma molecular biomarkers." (PMID 37380984, 2023). "We further explored the relationship between ISG20 and the expression of marker genes of tumor-associated macrophages (TAMs) and M1 and M2 macrophages in TCGA glioma." (PMID 37380984, 2023). "In the current study, we comprehensively illustrated the potential function of ISG20, its predictive value in stratifying clinical prognosis, and its association with immunological characteristics in glioma by adopting a bioinformatics methodology." (PMID 37380984, 2023). "For Isg20 we detected a lower expression in glioma-associated macrophages/monocytes when compared to naïve monocytes." (PMID 25658639, 2015). "In addition, ISG20 expression has been also associated with glioma and radioresistance in oral cancer cells and other types of cancer." (PMID 35174977, 2022). "Higher expression of ISG20 was associated with suppressed adaptive immune responses, increased infiltration of monocyte-derived macrophages and neutrophils, higher tumor grade, and poorer clinical outcome in glioma." (PMID 34285922, 2021). "Furthermore, the stratification analysis showed that high ISG20 expression may predict unfavorable OS in glioma patient subgroups with different age, sex, IDH mutation, 1p19q codeletion, and MGMT methylation (all P < 0.05)." (PMID 37380984, 2023). "In recent years, ISG20 has been involved in the progression of various tumors, such as cervical cancer, kidney cancer, and glioma." (PMID 39428941, 2025). "ISG20 is expressed on M2 macrophages, and can serve as a novel indicator for predicting the malignant phenotype and clinical prognosis in glioma patients." (PMID 37380984, 2023). "Our study revealed that upregulation of ISG20 is positively correlated with unfavorable overall survival (OS) among patients with glioma." (PMID 37380984, 2023). "To determine the precise immune function of ISG20, we analyzed the correlation coefficient between ISG20 and the 22 types of immune cells infiltrating the glioma TME." (PMID 37380984, 2023). "To be more specific, we further explored the prognostic value of ISG20 in patients with glioma by analyzing the TCGA glioma dataset." (PMID 37380984, 2023). "Nevertheless, the expression of ISG20 in gliomas, its impact on patient prognosis, and its role in the tumor immune microenvironment have not been fully elucidated." (PMID 37380984, 2023). "The results revealed that compared with low-grade gliomas, the intensity of CD163 protein in high-grade gliomas was also enhanced (P < 0.05), and there was a good match between ISG20 and CD163 expression in the serial sections." (PMID 37380984, 2023). "Regarding MGMT methylation status, ISG20 was overexpressed in glioma tissues with unmethylated MGMT (P < 0.001)." (PMID 37380984, 2023). "In correlation analysis, we observed the most positive correlation between M2 macrophage infiltration and ISG20 expression, prompting us to gain insight into the cellular distribution of ISG20 on macrophages and its role in macrophage polarization in gliomas." (PMID 37380984, 2023). "In the current study, we found that ISG20 mRNA expression was significantly higher in gliomas than in normal tissues." (PMID 37380984, 2023).